RNF144A (ring finger protein 144A)
Diseases named in the same sentence as RNF144A in open-access papers (continued):
Sharing a sentence is not in itself a finding about the gene and the disease.
viral infection (1 paper, 2020). "Although up-regulation of teleost [i.e., grass carp (Ctenopharyngodon idellus)] rnf144a in response to viral infection was previously reported, further studies are needed to characterise the function of this and other identified transcripts in fish antibacterial responses." (PMID 33193341, 2020).
cancer (13 papers, 2017 to 2026). A tumor composed of atypical neoplastic, often pleomorphic cells that invade other tissues. "RNF144A is frequently mutated or epigenetically silenced in cancers, providing a theoretical basis for assessing the loss of function of RNF144A in tumorigenesis." (PMID 40756570, 2025). "Research has demonstrated that RNF144A expression is frequently dysregulated in cancer cells and that either overexpression or downregulation can significantly impact the development and spread of tumors." (PMID 38313020, 2024). "RNF144A maintains EGFR signaling to encourage cancer cell proliferation that is dependent on EGF." (PMID 38313020, 2024). "It has been discovered that the gene RNF144A is involved in cancer." (PMID 38313020, 2024). "However, the functional relevance of RNF144A to cancer development and therapeutic response remains undefined." (PMID 29212245, 2017). "We also demonstrated that the level of RNF144A is increased in response to the stress and further downregulates VRK2 through proteasomal degradation in various types of cancer cells." (PMID 40204710, 2025). "Another ubiquitin ligase, RNF144A, was reported to exert a positive effect on cell proliferation in EGF-dependent human cancer and immortalized embryonic cell line models, by maintaining EGFR expression." (PMID 35634494, 2022).
tumor (10 papers, 2017 to 2025). "Together, these results indicate that RNF144A acts as an emerging tumor suppressor, but its underlying mechanisms still remain poorly understood." (PMID 35103856, 2022). "Ring finger protein 144A (RNF144A), a poorly characterized member of the RING-in-between-RING family of E3 ubiquitin ligases, is an emerging tumor suppressor, but its underlying mechanism remains largely elusive." (PMID 35103856, 2022). "As RNF144A affects PARP1 protein abundance, we further demonstrated that the expression levels of RNF144A are associated with cellular sensitivity to olaparib in MDA-MB-231 cells in vitro and xenograft mouse tumor models." (PMID 29212245, 2017). "RNF144A interacted with HSPA2 can promote tumor growth and progression." (PMID 34412642, 2021). "The tumor-promoting conditions and mechanisms are as follows: Formation of the RNF144A-ALK complex leads to RNF144A-promoted LUAD." (PMID 40756570, 2025). "Emerging evidence shows that ring finger protein 144A (RNF144A), a poorly characterized member of the Ring‐between‐Ring (RBR) family of E3 ubiquitin ligases, is a potential tumor suppressor gene." (PMID 29473320, 2018).
infectious disease (1 paper, 2025). A disorder directly resulting from the presence and activity of a microbial, viral, or parasitic agent in humans. "In addition to being associated with tumors, RNF144A and RNF144B play important roles in neurological and infectious diseases." (PMID 40756570, 2025).
RNF144A also shares sentences with these, for which no sentence is quoted: chordoma (1 paper); endometrial cancer (1); gastric cancer (1); glioblastoma (1); glioma (1); head and neck squamous cell carcinoma (1); hepatocellular carcinoma (1); infection (1); leukemia (1); lung carcinoma (1); lymphoma (1); multiple myeloma (1); neurodevelopmental disorder (1); neurological disorders (1); prostate carcinoma (1); reproductive system disorder (1); reproductive tumors (1); respiratory diseases (1).